NOS3 (nitric oxide synthase 3)
Diseases named in the same sentence as NOS3 in open-access papers (continued):
Sharing a sentence is not in itself a finding about the gene and the disease.
gastric cancer (7 papers, 2021 to 2025). A primary or metastatic malignant neoplasm involving the stomach. "Analyses in public data sets gastric cancer tissues demonstrated that higher NOS3 expression was related to poor prognosis of patients with STAD." (PMID 33747912, 2021). "Immunohistochemical staining validated that NOS3 was an independent prognostic factor of gastric cancer." (PMID 33747912, 2021). "Immunohistochemical staining of tissue sections were used to validate the prognostic role of NOS3 in gastric cancer patients." (PMID 33747912, 2021). "The mechanism of these signaling pathways involved in NOS3 regulation of gastric cancer needs further study." (PMID 33747912, 2021). "Furthermore, experiments and analyses in our gastric cancer tissues also indicated that higher NOS3 protein level was closely related to shorter OS of gastric cancer patients." (PMID 33747912, 2021). "Furthermore, cox proportional-hazards model was used to validate the potential of NOS3 as a prognostic factor in gastric cancer." (PMID 33747912, 2021). "In summary, NOS3 was an independent prognostic factor for patients with gastric cancer." (PMID 33747912, 2021). "NOS3 was an independent prognostic factor for patients with gastric cancer." (PMID 33747912, 2021). "Subsequently, NOS3 protein level was individually assessed in gastric cancer tissues." (PMID 33747912, 2021). "Furthermore, the expression pattern of NOS3 protein was explored in clinical tissue samples to validate the role of NOS3 in gastric cancer." (PMID 33747912, 2021). "Therefore, we further analyzed the potential signaling pathways participating in NOS3 promoting gastric cancer." (PMID 33747912, 2021). "A pan-cancer investigation revealed that the expression of NOS3 correlates with the response of STAD to QS-11 and brivinib, indicating the importance of the protein in the treatment of gastric cancer." (PMID 36276268, 2022). "Reduced the phosphorylation of NOS3, thereby inhibiting the MAPK signaling pathway, and finally suppressed the gastric cancer peritoneal dissemination by inhibiting the EMT process." (PMID 35011278, 2021). "VAMP3 and NOS3 were investigated independently, and knockdown or overexpression of VAMP3 did not affect NOS3 expression in gastric cancer cells or in exosomes." (PMID 38802855, 2024). "Studies on NOS3 expression in tumors are still scarce, and the functions of NOS3 in tumor pathogenesis, especially in gastric cancer, are not comprehensively understood." (PMID 33747912, 2021). "Based on NOS3 protein expression levels, gastric cancer patients (N = 90) were divided into NOS3 positive (N = 45) and NOS3 negative (N = 45) group." (PMID 33747912, 2021). "Also, NOS3 was reported to serve as an oncogene in gastric cancer, which supports the predicted result on the expression relationship between LINC00887 and NOS3 in this study In a word, the expression trend of LINC00887 is relatively consistent with that of most immunosuppressive genes." (PMID 36060659, 2022).
glomerulosclerosis (7 papers, 2007 to 2025). A hardening of the kidney glomerulus caused by scarring of the blood vessels. "We have shown that injury to glomerular endothelial cells precedes podocyte damage and the development of proteinuria and glomerulosclerosis in adriamycin-induced nephropathy, while nitric oxide synthase 3 (NOS3/eNOS) deficiency accelerates kidney injury in this model." (PMID 24391884, 2013). "Accordingly, we developed an animal model by STZ and HFD induction, showing key characteristics of DKD such as high blood glucose and glomerular sclerosis that agree with the Nos3−/− mouse model, which has been widely used in DKD studies." (PMID 38873818, 2025).
hepatocellular carcinoma (7 papers, 2013 to 2025). A malignant tumor that arises from hepatocytes. "In fact, patients with hepatocellular carcinoma (HCC) display high levels of NO derivates in serum and tumors associated with increased NOS2 and NOS3 expression." (PMID 34200849, 2021). "We investigated whether or not nitric oxide synthase 3 (NOS3) rs2070744 genotypes can affect the response for lenvatinib treatment in patients with hepatocellular carcinoma (HCC)." (PMID 33051476, 2020).
periodontitis (7 papers, 2020 to 2024). An acute or chronic inflammatory process that affects the tissues that surround and support the teeth. "Wei and colleagues showed that activation of STAT1 pathway was linked with endothelial nitric oxide synthase gene knockout‐related (Nos3‐/‐) mouse model of periodontitis." (PMID 39436204, 2024). "In this study, an experimental periodontitis model was established in hypertensive mice (Nos3−/−) to investigate the effect of periodontitis on hypertension‐related kidney damage." (PMID 33448153, 2021). "A hypertensive renal injury mouse model was established with Nos3 knockout mice, and a periodontitis model was established by implantation with the oral bacteria Porphyromonas gingivalis." (PMID 33448153, 2021). "As it has been shown, in the Polish population, patients suffering from periodontitis carry the polymorphic rs2070744 genotype in the promoter section of the NOS3 gene located on chromosome 7q35–36 significantly more frequently." (PMID 32245286, 2020). "The hub genes identified in the periodontitis comorbidity network, such as TNF, IL6, PTGS2, IL10, and NOS3, play pivotal roles in connecting periodontitis with various systemic diseases, as indicated by their high connectivity degrees." (PMID 39337647, 2024).
sarcopenia (7 papers, 2020 to 2025). Progressive decline in muscle mass due to aging which results in decreased functional capacity of muscles. "The same authors described endothelial nitric oxide synthetase gene—NOS3 (rs1799983 GG genotype) to increase the sarcopenia risk almost twofold." (PMID 38397196, 2024). "It should be noted that the SNPs showing associations in the present study (ACTN3 rs1815739, MTHFR rs1801131, and MTHFR rs1537516) are different from our previous study that identified associations of FTO, TRHR, ESR1, and NOS3 gene variants with sarcopenia." (PMID 34768452, 2021). "The current study is the first to identify the NOS3 rs1799983 GG genotype as a risk factor for sarcopenia, with over 2-fold higher risk compared to T-allele carriers, for sarcopenia in the elderly." (PMID 32076017, 2020). "Based on the %SMM definition, the SNPs FTO rs9939609, ESR1 rs4870044 and NOS3 rs1799983 were associated with sarcopenia." (PMID 32076017, 2020). "This study analyzed 24 SNPs but found that only 4 SNPs (FTO rs9939609, ESR1 rs4870044, NOS3 rs1799983, and TRHR rs7832552) were significantly associated with sarcopenia." (PMID 40428823, 2025). "A previous study on genetic markers for sarcopenia identified the loci near FTO, ESR1, NOS3, KLF5, and HLA-DQA1 to be associated with physical phenotypes, such as low handgrip strength and decreased LBM24–26." (PMID 35241739, 2022). "Several studies have associated single-nucleotide polymorphisms (SNPs) with muscle mass and strength in the elderly, and recently our group found that sarcopenia in elderly women was associated with polymorphisms in FTO, TRHR, ESR1, and NOS3." (PMID 34768452, 2021). "Four SNPs were associated with the %SMM and SMI definitions of sarcopenia; FTO rs9939609, ESR1 rs4870044, NOS3 rs1799983 and TRHR rs7832552." (PMID 32076017, 2020).
thrombosis (7 papers, 2013 to 2025). "The allele and genotype frequencies of the NOS3 polymorphism (rs1799983) were significantly different between subjects with deep vein thrombosis and control subjects." (PMID 23922896, 2013). "Our objective was to evaluate the association between the NOS3 polymorphism (rs1799983) and deep vein thrombosis after orthopedic surgery in Chinese Han population." (PMID 23922896, 2013). "Nitric oxide synthase 3 (NOS3) expression and NO levels are impacted by MiR-582 overexpression in deep vein thrombosis, which contributes to the pathophysiology." (PMID 41361288, 2025).
angina pectoris (6 papers, 2009 to 2025). The symptom of paroxysmal pain consequent to MYOCARDIAL ISCHEMIA usually of distinctive character, location and radiation. "The NOS3 (rs2070744) (T/C) polymorphism results in reduced eNOS expression and has been clinically associated with cardiovascular events, such as angina and myocardial infarction." (PMID 33539452, 2021).
cerebral infarction (6 papers, 2010 to 2024). An ischemic condition of the brain, producing a persistent focal neurological deficit in the area of distribution of the cerebral arteries. "Also, the NOS3 gene was upregulated 24 h after cerebral infarct in both areas but not after 3 d." (PMID 23284893, 2012).
erectile dysfunction (6 papers, 2016 to 2025). Persistent or recurrent inability to achieve or to maintain an erection during sexual activity. "One significant polymorphism examined in this study is rs1799983 of the NOS3 gene, which has been associated with erectile dysfunction." (PMID 40943369, 2025).
Hyperinsulinemia (6 papers, 2009 to 2025). An increased concentration of insulin in the blood. "In contrast, NOS3 deficiency had been found to be associated with reduced fatty acid oxidation, elevated circulating triglyceride levels, and fasting hyperinsulinemia." (PMID 40413611, 2025). "ACE and NOS3 are associated with inflammation, hyperinsulinism, and metabolic diseases." (PMID 19208189, 2009).
renal fibrosis (6 papers, 2013 to 2025). A final common manifestation of a wide variety of chronic kidney diseases characterized by glomerulosclerosis and tubulointerstitial fibrosis. "However, the mechanism linking a loss of NOS3 expression to increased renal fibrosis is most likely to involve the central TGF-β1/Smad3 pro-fibrotic signalling pathway." (PMID 24391884, 2013).
resistant hypertension (6 papers, 2009 to 2025). "The aim of the present study was to investigate if the -786T>C and G894T (Glu298Asp) polymorphisms of the NOS3 gene were associated with resistant hypertension." (PMID 19650939, 2009). "We compared the distribution of the -786T>C and G894T (Glu298Asp) NOS3 polymorphisms in patients with controlled and resistant hypertension." (PMID 19650939, 2009). "In summary, -786CC NOS3 genotype could be a significant contributing factor to resistant hypertension and may be a genetic marker of genetic predisposition to resistant hypertension." (PMID 19650939, 2009). "-786CC NOS3 genotype increase the susceptibility to suffer resistant hypertension and may be a genetic marker of genetic predisposition to resistant hypertension." (PMID 19650939, 2009). "Our data suggest that promoter variants in the NOS3 gene may play a role in the pathogenesis of resistant hypertension." (PMID 19650939, 2009). "However, Analysis of the distribution of -786T>C NOS3 genotypes show that genotype -786CC is more frequent in resistant hypertension patients." (PMID 19650939, 2009). "However, we found differences in the distribution of the -786T>C NOS3 genotypes being genotype CC more frequent in the resistant hypertension group." (PMID 19650939, 2009). "Thus, our results indicate that the G894T (Glu298Asp) polymorphism of the NOS3 gene did not modify the susceptibility to suffer resistant hypertension in our population." (PMID 19650939, 2009). "Polymorphisms in the endothelial nitric oxide synthase (NOS3) gene have been associated with high blood pressure levels, but not with resistant hypertension." (PMID 19650939, 2009).
schizophrenia (6 papers, 2018 to 2024). A major psychotic disorder characterized by abnormalities in the perception or expression of reality. "In another population of patients with schizophrenia, we have demonstrated that the NOS3 786C/T polymorphism correlates with MetS." (PMID 38540239, 2024). "An apparent close connection between the ketamine and BPC 157 was noted in the genes’ expression analysis in brain tissue, using Nos1, Nos2, Nos3, Plcg1, Prkcg, Ptgs2, and Ptk2 all associated with schizophrenia presentation." (PMID 35884767, 2022). "This was done with the genes’ expression analysis in brain tissue, using Nos1, Nos2, Nos3, Plcg1, Prkcg, Ptgs2, and Ptk2, all associated with schizophrenia presentation." (PMID 35884767, 2022).
Anxiety (5 papers, 2022 to 2025). Intense feelings of nervousness, tension, or panic often arise in response to interpersonal stresses. "The expressions of angiogenic protein genes (NOS3, VEGF) and HIF-1a were decreased significantly in the current study in ewes showed anxiety temperament than the calm ones (P < 0.05)." (PMID 40625796, 2025).
Arrhythmia (5 papers, 2012 to 2022). Any cardiac rhythm other than the normal sinus rhythm. "Previous studies have observed an increased incidence of arrhythmias in NOS3−/−mice." (PMID 36059969, 2022). "Besides, NOS3 mediates the stretch dependence of Ca2+ release in cardiomyocytes, which is pivotal protection in the prevention of arrhythmia." (PMID 34859062, 2021). "While alterations in K+ currents can contribute to the increased incidence of these triggered arrhythmias, we did not observe any difference in K+ currents in NOS3−/− myocytes." (PMID 22970362, 2012).
chronic obstructive pulmonary disease (5 papers, 2011 to 2025). A chronic and progressive lung disorder characterized by the loss of elasticity of the bronchial tree and the air sacs, destruction of the air sacs wall, thickening of the bronchial wall, and mucous accumulation in the bronchial tree. "The polymorphism of human Nos3 gene is associated with high-altitude pulmonary edema and PH in patients with chronic obstructive pulmonary disease." (PMID 22171643, 2011).
cognitive decline (5 papers, 2021 to 2025). "We evaluated the association of four single-nucleotide polymorphisms (VEGF, VEGFR2 and NOS3) with diagnosis and rate of cognitive decline in AD and VaD in a Spanish case–control cohort (150 VaD, 147 AD and 150 controls)." (PMID 37596325, 2023).
diabetic retinopathy (5 papers, 2013 to 2025). "In addition, the vascular endothelial growth factor signaling pathway that involving many target proteins, such as INSR, NOS3, PTGS2, and vascular endothelial growth factor A (VEGFA), plays a key regulatory role in diabetic retinopathy." (PMID 32265717, 2020).
male infertility (5 papers, 2014 to 2023). The inability of the male to effect fertilization of an ovum after a specified period of unprotected intercourse. "But we showed that NOS3 rs1799983 was significantly associated with risk of male infertility and sperm DNA damage." (PMID 25517965, 2014). "Previous studies have examined the relationship of NOS3 gene polymorphisms and male infertility, but the results were conflicting." (PMID 25517965, 2014). "Of five NOS gene polymorphisms investigated in the present study, we found NOS3 rs1799983 might cause oxidative sperm DNA damage, thereby contributing to male infertility." (PMID 25517965, 2014). "In the present case-control study, our results revealed that NOS3 rs1799983 (G894T) was associated with a borderline significantly increased risk of male infertility (GT vs GG: adjusted OR = 1.30, 95% CI: 1.00–1.70; GT+TT vs GG: adjusted OR = 1.34, 95% CI: 1.03–1.74; Ptrend = 0.020)." (PMID 25517965, 2014). "Recently, the associations between NOS3 gene polymorphisms and male infertility were also reported." (PMID 25517965, 2014). "Thus, the aim of the present study was to investigate the associations between five polymorphisms in NOS genes (NOS1 rs2682826, NOS1 rs1047735, NOS2 rs2297518, and NOS2 rs10459953, and NOS3 rs1799983) and male infertility risk and also sperm DNA damage in a Chinese population." (PMID 25517965, 2014). "A case-control study revealed that NOS3 rs1799983, a NOS gene polymorphism, increases the risk of oxidative sperm DNA damage, which leads to male infertility." (PMID 37180698, 2023). "NOS3-786CC, 894TT and 4aa genotype were significantly more frequent in infertile subjects, and 786C, 894T, and 4a alleles contributed to poor semen parameters,suggesting a significant relationship between NOS genotypes and the phenotype of male infertility." (PMID 25517965, 2014).
melanoma (5 papers, 2009 to 2022). A malignant, usually aggressive tumor composed of atypical, neoplastic melanocytes. "Downregulation of Nos3 also decreased cell viability, clonogenicity capability, and anoikis resistance of 4C11+ melanoma cells." (PMID 34502464, 2021). "We found decreased Nos3 expression in Mn3 and Mn5 cells compared to 4C11+ metastatic melanoma cells." (PMID 34502464, 2021). "We demonstrated increased Nos3 mRNA expression in 4C11+ metastatic melanoma cells, as observed during melanocyte anchorage blockade impediment." (PMID 34502464, 2021). "The expression and activity of NOS3 was reported to play a role in gMDSC suppression using a murine model of malignant melanoma." (PMID 28835242, 2017). "Moreover, in B16F10 melanoma tumors from chronically stressed animals, Nos3 is overexpressed and contributes to tumor development." (PMID 34502464, 2021). "Moreover, analysis from TCGA showed increased NOS3 expression along with melanoma progression." (PMID 34502464, 2021). "Furthermore, our data analysis showed that 14% of the melanoma patients have genetic alteration on NOS1 gene, 8% on NOS2 and 18% on NOS3." (PMID 35326089, 2022). "Our data from patient biopsies, showed that there were no significant alterations in the NOS1 and NOS3 expression levels during melanoma progression." (PMID 35326089, 2022). "Therefore, increased ROS levels observed in 4C11+ melanoma cells could be a result of a disturbance between BH4 amount and Nos3 expression." (PMID 34502464, 2021).
autosomal dominant polycystic kidney disease (4 papers, 2009 to 2024). Autosomal dominant form of polycystic kidney disease. "A recent meta-analysis of 13 studies found that two NOS3 gene polymorphisms (rs1799983, R2 = 0.189 with rs3918226 and the intron 4 VNTR a/b polymorphism) significantly increased ESKD risk in autosomal dominant polycystic kidney disease (ADPKD) patients." (PMID 38858654, 2024).
cardiac arrest (4 papers, 2012 to 2025). Cessation of breathing and/or cardiac function. "We have reported a substantial increase in post-cardiac arrest injury seen in NOS3-/- mice." (PMID 31398213, 2019).
cardiomyopathies (4 papers, 2017 to 2025). "The review identified key gene variants affecting athletic performance: endurance (AMPD1, PPARGC1A), power (ACTN3, NOS3), strength (PPARG), and injury susceptibility (COL5A1, MMP3), while also examining inherited conditions like cardiomyopathies (MYH7, MYBPC3)." (PMID 40724525, 2025). "We showed that NOS3, CAV1 and SIRT1 are expressed in the cardiomyopathies as well as other non-cancer and non-heart related diseases." (PMID 36385157, 2022).
colon cancer (4 papers, 2015 to 2025). "NOS2 and NOS3 promote colon cancer’s migration and invasive capacity by activating soluble guanylate cyclase." (PMID 40642105, 2025). "Different NOS3 and NOS1 polymorphisms described in colorectal tissue are suspiciously associated with the development of colon cancer." (PMID 40642105, 2025). "In contrast, NOS3 expression was reduced in the HCT116 colon cancer cell line in the same study." (PMID 34200849, 2021). "NOS3 expression was found to be higher in total extracts from colon cancer biopsies compared to non-tumoral adjacent tissue." (PMID 34200849, 2021).
endometriosis (4 papers, 2005 to 2025). The growth of functional endometrial tissue in anatomic sites outside the uterine body. "Kim’s research indicated that the Glu298Asp polymorphism of NOS3 might regulate angiogenesis and influence individual susceptibility to endometriosis." (PMID 40227209, 2025).